LGALS4 (galectin 4)
Description:
Galectin that binds lactose and a related range of sugars. May be involved in the assembly of adherens junctions.
Synonyms: L36LBP; GAL4
Tractability: Small molecule: a structure with a bound ligand is known; a high-quality ligand is known. Antibody: its Gene Ontology location is reachable by antibodies, with high confidence. PROTAC: its protein half-life has been measured; a small molecule that binds it is known.
Target class: Other cytosolic protein
Gene: Protein-coding gene on chromosome 19 (38,801,671 to 38,813,070, reverse strand). Ensembl gene ENSG00000171747.
Subcellular location (Human Protein Atlas): Plasma membrane
Gene Ontology:
Molecular function: protein binding; carbohydrate binding; galactoside binding
Biological process: cell adhesion
Cellular component: extracellular matrix; cytosol; plasma membrane; extracellular region
Genetic constraint (gnomAD): Loss-of-function variants: 38 observed, 42.24 expected, observed/expected ratio (o/e) 0.9, 90% interval 0.69 to 1.18. The upper end of that interval is the gene's LOEUF score, 1.18, which puts it in group 5 of 6, group 1 being the genes least tolerant of losing a copy. Missense variants: 397 observed, 453.81 expected, observed/expected ratio (o/e) 0.87, 90% interval 0.81 to 0.95. Synonymous variants: 160 observed, 173.27 expected, observed/expected ratio (o/e) 0.92, 90% interval 0.81 to 1.05.
Homologues: Orthologues: chimpanzee LGALS4 (99% identical), macaque LGALS4 (93% identical), pig LGALS4 (80% identical), dog LGALS4 (77% identical), mouse Lgals4 (77% identical), rat Lgals4 (77% identical), guinea pig LGALS4 (71% identical), rabbit LGALS4 (57% identical), tropical clawed frog lgals4 (55% identical), tropical clawed frog lgals4.2 (50% identical), zebrafish lgals4 (38% identical), Caenorhabditis elegans lec-3 (32% identical), and 6 more. Paralogues in human: LGALS9 (40% identical), LGALS9B (40% identical), LGALS9C (40% identical), LGALS8 (35% identical), LGALS12 (29% identical), LGALS3 (22% identical), LGALSL (18% identical), LGALS7 (16% identical), LGALS7B (16% identical), LGALS1 (14% identical), LGALS14 (13% identical), LGALS16 (12% identical), and 4 more.
Diseases named in the same sentence as LGALS4 in open-access papers:
LGALS4 is named in the same sentence as 199 diseases in open-access papers, as found by Europe PMC text mining. Sharing a sentence is not in itself a finding about the gene and the disease. The quoted sentences say what the papers report.
colorectal cancer (33 papers, 2006 to 2025). A primary or metastatic malignant neoplasm that affects the colon or rectum. "Galectin-4 which has been detected in many cancers has association with the development and progression of pancreatic carcinoma, hepatocellular carcinoma, colorectal cancer (CRC), breast carcinoma, gastric cancer, and lung cancer." (PMID 27017379, 2016). "In other studies, lower expression of galectin-4 was associated with an advanced form of colorectal cancer, and galectin-4 overexpression could improve the efficacy of camptothecin treatment." (PMID 36873388, 2023). "Interestingly, extracellular galectin-4 could induce apoptosis in galectin-4-deficient colorectal cancer cells, while in galectin-4-positive colorectal cancer cells, inflammatory chemokine gene expression and secretion were downregulated." (PMID 36873388, 2023). "In addition, the twin single nucleotide polymorphisms (SNPs) could potentially be related to galectin-4 upregulation via deletion and insertion of new transcription factor binding sites in colorectal cancer (CRC)." (PMID 27017379, 2016). "In contrast, LGALS4 is found to be downregulated in colorectal cancer, and its increased expression can impede cellular growth, trigger cell cycle arrest, augment apoptosis induced by 5-fluorouracil, inhibit aerobic glycolysis, and diminish cell proliferation." (PMID 41311582, 2025). "Upregulation of galectin-4 was observed in patients with advanced liver cancer, intraductal breast cancer, and gastric and colorectal cancers." (PMID 36873388, 2023). "LGALS4 is a Protein Coding gene, the expression of this gene is restricted to the small intestine, colon, and rectum, and it is under-expressed in colorectal cancer." (PMID 34149811, 2021). "Low expression of LGALS4 is associated with poor survival rate, while high expression of COL1A2 and the new reported gene DARS is linked to poor survival rate in colorectal cancer patients." (PMID 34249670, 2021). "Reduced expression of galectin-4 was also described in colorectal cancer, skin cancer and prostate cancer." (PMID 31832021, 2019). "The first transcript was LGALS4 which predominantly expressed in small intestine, colon, and rectum, and was under expressed in colorectal cancer." (PMID 31737124, 2019). "Galectin-4 has anticancer properties and has been shown to suppress colorectal cancer; knockdown of it promotes tumorigenesis, and lower levels of galectin-4 expression were observed in inflamed precursor lesions of colorectal cancer." (PMID 29950926, 2018). "The expression level of galectin-4 was observed to be significantly increased up to 31-fold in the serum of colorectal cancer patients compared with healthy control group." (PMID 27017379, 2016). "In contrast, the cellular expression of galectin-4 has been reported to be lower in colorectal adenocarcinomas than in normal colon tissues, suggesting that galectin-4 have tumor-suppressive effects in the development and progression of colorectal carcinomas." (PMID 24339976, 2013). "Moreover, the upregulation of LGALS4 inhibits aerobic glycolysis in colorectal cancer cells, resulting in decreased glucose dependency and reduced glycolytic activity." (PMID 41311582, 2025). "Studies reveal that heightened LGALS4 expression can lead to a reduction in cell proliferation by nearly 50% and double the apoptosis rate, emphasizing its role in suppressing the growth of colorectal cancer cells." (PMID 41311582, 2025). "Galectin-4 (Gal4) has been suggested to function as a tumor suppressor in colorectal cancer (CRC)." (PMID 35742860, 2022). "Since T-cell response can help remove cancer cells, the fact that galectin-4 can promote mucosal T-cell apoptosis and also suppress colorectal cancer seems counterintuitive and suggests that there are mechanisms in colorectal inflammation and cancer prevention that warrant further studies." (PMID 29950926, 2018).
colorectal cancer (continued). "Galectine-4 (gal-4), encoded by the LGALS4 gene, was recently shown to exhibit a tumor suppressive effect in colorectal carcinoma and pancreatic adenocarcinoma, although how the expression of this gene is regulated remains unknown." (PMID 28423602, 2017). "Serum antibodies against LGALS4 have, however, been reported in a patient with colorectal cancer." (PMID 16508639, 2006). "LGALS4 is significantly downregulated in colorectal cancer, and its overexpression can inhibit cell growth, induce cell cycle arrest, enhance 5-fluorouracil-induced apoptosis, and suppress aerobic glycolysis, suggesting its potential as a novel therapeutic target for colorectal cancer." (PMID 41311582, 2025). "Since it has been shown that blocking galectin-4 in colorectal cancer cells induced the release of IL-6 and other cytokines, including CXCL1, CCL2, CCL5, and CXCL10, it is tempting to speculate that these cytokines are responsible for the effects of galectin-4 on immune cells." (PMID 36139125, 2022). "Using Random Survival Forest (RSF) analysis with importance scoring, we identified seven key prognostic genes (CD24, SLC25A5, HSPB1, CD9, SPIMK1, LGALS4, and CEACAM5), which were subsequently designated as the Colorectal cancer Survival Signature (CSS)." (PMID 40777020, 2025). "Differentiation of human colorectal carcinoma cell lines LS174T and HT-29 into enterocyte-like lineage is accompanied by increasing galectin-4 mRNA expression." (PMID 32731422, 2020). "It is a dual function protein: promote cell proliferation and chemokine secretion in galectin-4-expressing colorectal cancer cells, but induce apoptosis in galectin-4-negative colorectal cancer cells." (PMID 31737124, 2019).
pancreatic cancer (19 papers, 2013 to 2025). "A study discovered that high expression of galectin-4 was negatively correlated with lymphatic metastasis of pancreatic cancer and positively linked with T cells in vivo." (PMID 36428567, 2022). "Interestingly, galectin-4 expression is associated with reduced lymph node metastasis and led to reduced migration and metastasis of pancreatic cancer cells." (PMID 32055023, 2020). "The same is the case for Galectin-3 (LGALS3) and Galectin-4 (LGALS4), associated with gastro-intestinal cancers, which are downregulated in colorectal (COREAD) but upregulated in pancreatic cancer (PAAD)." (PMID 38384845, 2024). "The data show that galectin 4 blocks antitumor immunity and identify galectin 4 as a potential novel drug target for treating pancreatic cancer." (PMID 36478037, 2023). "Taken together, our results suggest that high expression of galectin-1 and low levels of galectin-4 or galectin-9 are predictors of worse prognosis in pancreatic cancer patients." (PMID 31832021, 2019). "Taken together, galectin-4 acts as a tumor suppressor in CRC, pancreatic cancer, hepatocellular cancer, and ileal carcinoids, whereas galectin-4 functions as a tumor promoter in lung and gastric cancer." (PMID 27017379, 2016). "In this study we have focused on the role of galectin-4 (Gal-4) in metastasis of pancreatic cancer cells." (PMID 23824659, 2013). "Moreover, LGALS4 was shown to induce apoptosis in T cells by binding CD3ε/δ and driving immune evasion in pancreatic cancer." (PMID 39857769, 2025). "Galectin 4 is a cancer cell–produced protein abundant in pancreatic tumors." (PMID 36478037, 2023). "Galectin-4 acts as an inhibitor of immune evasion of tumor cells in pancreatic cancer." (PMID 36428567, 2022). "This suggested a special significance of galectin-4 in pancreatic cancer." (PMID 36428567, 2022). "In a mass spectrometry-based study, galectin 4, a group of carbohydrate-binding proteins involved in neoplastic development and progression, was identified as a down-regulated protein in short-term survivors of pancreatic cancer and correlated with an ER." (PMID 34064540, 2021). "In addition, analysis of a pancreatic cancer single-cell RNA-seq data set published by Peng and colleagues confirmed that epithelial cells had the highest LGALS4 mRNA expression, and that the expression was higher in cancer ductal cells compared with normal ductal cells." (PMID 36478037, 2023). "In previous studies, the transient transfection of LGALS4 into pancreatic carcinoma, gastric cancer cells oligodendrocytes and CRC cell lines was already used to investigate the intracellular functions of Gal4." (PMID 35742860, 2022). "Our meta-analysis supported the various function of different galectin subtypes in cancer prognosis, that converse to galectin-1, high levels of galectin-4 or galectin-9 predicted better OS and DFS in pancreatic cancer." (PMID 31832021, 2019). "Intracellularly, galectin-4 functions as a tumor suppressor, and its downregulation is an important event in the tumorigenesis of CRC, pancreatic cancer, and hepatocellular cancer, whereas it functions conversely in lung cancer and gastric cancer." (PMID 27017379, 2016). "In pancreatic cancer, we found that LGALS4 was amplified in 8% to 18% of sequenced tumors, which in part explains the increased protein expression of gal 4 in PDAC." (PMID 36478037, 2023). "Galectin-4 is highly expressed in pancreatic cancer while almost not in normal tissues." (PMID 36428567, 2022).
colon carcinoma (17 papers, 2010 to 2025). "Galectin-4-expressing colon cancer cells were inhibited relatively at low fucoidan concentrations, supporting that galectin-4 is involved in the suppressive effects of fucoidan." (PMID 41009793, 2025). "We found that NR5A2, PPARGC1A and LGALS4 were all down-regulated in colon cancer cell lines, in comparison with normal colon epithelial cell line." (PMID 36440228, 2022). "It this study, we found the consistent results by showing that NR5A2, PPARGC1A and LGALS4 were down-regulated in colon cancer cell lines and downregulation of the three genes were related to poor prognosis." (PMID 36440228, 2022). "By contrast, LMNB1 was among the top25 down-regulated proteins in quantitative stable isotope labeling using amino acids in cell culture (SILAC) proteomic analysis of human colon cancer cells induced by galectin-4." (PMID 36005596, 2022). "Only eight genes (UCN, TRIM, RBCK1, TPM2, CD36, NMB, PPARGC1A, and LGALS4) significantly affected the OS in patients with colon cancer (P < 0.05)." (PMID 35572595, 2022). "One target gene of HNF4A is galectin 4, which was described as tumor-suppressor in colon cancer, but also pancreatic duct adenocarcinoma, and was accordingly positively associated with high CDX1 mRNA expression in the current study." (PMID 30909444, 2019). "For example, decreased levels of RPL29 induced differentiation of LS174T colon cancer cells with increased expression of two known markers of differentiation, galectin-4 and mucin-2." (PMID 20221446, 2010). "It was reported that downregulation of LGALS4 was related to poor clinical outcome in colon cancer." (PMID 36440228, 2022). "In addition, knockdown of this gene stimulates cell differentiation accompanied by the upregulation of two potential cell differentiation markers mucin-2 and galectin-4 in colon cancer cells." (PMID 33004906, 2020). "In contrast, breast and colon carcinomas express galectin-4 almost exclusively in the cytoplasm." (PMID 24339976, 2013). "By regression analysis, 6 immune-related DEGs (AEN, F2RL1, NR3C2, PPARGC1A, LGALS4, and XDH) were identified as potential prognostic factors, of which AEN, LGALS4, and XDH were used to construct a risk score model, which can effectively predict overall survival (OS) in colon cancer patients." (PMID 36589748, 2022). "Based on the observations, galectin-4 could have divergent function in the development and progression of cancer, depending on its localization in lung adenocarcinoma, compared to that of breast and colon carcinomas." (PMID 24339976, 2013). "In our study, based on the colon cancer immune gene datasets, we used WGCNA to identify 21 immune-related hub genes affecting patients’ OS and constructed IRGPI based on 8 independent OS prognostic factors (UCN, TRIM58, RBCK1, TPM2, CD36, NMB, PPARGC1A, and LGALS4)." (PMID 35572595, 2022).
breast carcinoma (15 papers, 2002 to 2025). "Next, we investigated the frequency of LGALS4 (the gene encoding gal 4) alterations in GI, urinary, genital, respiratory, and breast carcinoma TCGA data sets." (PMID 36478037, 2023). "Because of distinct induction of galectin-4 in breast cancers, it may be a valuable diagnostic marker and target for the development of inhibitory carbohydrate-based drug." (PMID 23658855, 2010). "Galectin-4 is also released to extracellular space and high galectin-4 levels in the blood were observed in patients with metastatic colon, hepatocellular, and breast cancers (108, 344–, 346)." (PMID 36873388, 2023). "The free circulating level of galectin-4 in serum was significantly higher in patients with colon, hepatocellular, and breast cancer, in particular, those with metastasis." (PMID 27017379, 2016). "Recently, the levels of serum galectins, including that of galectin-4, were reported to increase in patients with colon and breast cancer." (PMID 24339976, 2013). "In tumors, LGALS4 expression increases in liver, gastric, breast cancer and mucinous epithelial ovarian cancer whereas it is down-regulated in colon adenocarcinoma." (PMID 19903339, 2009). "Galectin 4 has been found to be overexpressed in breast cancers and schirrous gastric cancer cell lines." (PMID 12402156, 2002). "Because galectin-4 is abnormally overexpressed in human breast cancers, as well as in other solid and hematopoietic malignancies, it may be a downstream product of the NF-κB." (PMID 27017379, 2016). "Moreover, the expression of galectin-4 might be a biomarker in serum of colon and breast cancer patients." (PMID 27017379, 2016).
gastric cancer (15 papers, 2002 to 2025). A primary or metastatic malignant neoplasm involving the stomach. "Chemically synthesized fucoidan analogs exhibited significant suppressive activity against the proliferation of gastric cancer cells, partly via a galectin-4-mediated pathway." (PMID 41009793, 2025). "The suppression of peritoneal metastasis of gastric cancer was observed by the knockdown of galectin-4 expression in a mouse model." (PMID 41009793, 2025). "In conclusion, fucoidan analogs with a strong affinity for galectin-4 are promising candidates for inhibiting the peritoneal metastasis of galectin-4-positive gastric cancer cells." (PMID 41009793, 2025). "Natural fucoidan also inhibited the proliferation of NUGC4 cells, a poorly differentiated gastric cancer cell line highly expressing galectin-4, in a concentration-dependent manner, as did MKN45 cells." (PMID 41009793, 2025). "Our previous study showed that galectin-4 plays an important role in the peritoneal dissemination of poorly differentiated gastric cancer cells." (PMID 41009793, 2025). "Next, we studied the effect of fucoidan on the proliferation of MKN45 cells, a widely used human gastric cancer cell line that expresses galectin-4 and is derived from a poorly differentiated adenocarcinoma." (PMID 41009793, 2025). "Our research has revealed that galectin-4 plays an important role in the peritoneal metastasis of gastric cancer cells." (PMID 41009793, 2025). "We observed that galectin-4 was highly expressed in poorly differentiated gastric cancer cells with high metastatic potential and that galectin-4 suppression notably impeded peritoneal metastasis in murine models." (PMID 39337716, 2024). "We recently found that galectin-4 participates in the peritoneal metastasis of malignant gastric cancer cells by interacting with several molecules, including c-MET and CD44, and affecting glycosylation." (PMID 39337716, 2024). "Our previous study demonstrated that galectin-4 participates in the peritoneal dissemination of poorly differentiated gastric cancer cells." (PMID 37569679, 2023). "Using knockout and knockdown techniques, we revealed that galectin-4 participates in the peritoneal dissemination of malignant gastric cancer cells by promoting cell proliferation and interacting with several molecules, including c-MET and CD44." (PMID 37569679, 2023). "In a previous study, we revealed that galectin-4 participates in the peritoneal dissemination of malignant gastric cancer cells by promoting cell proliferation and interacting with several molecules." (PMID 37569679, 2023). "Gene expression profiling using oligonucleotide arrays on 22 gastric cancer tissues revealed an increase in the expression of the genes LGALS4, FXYD3, SSRP1, and PRDX2 (Reference: GSE2685)." (PMID 35831348, 2022). "Conversely, in lung and gastric cancer, high level expression of galectin-4 was demonstrated to be an independent predictor for metastasis and correlated with poor clinical outcomes." (PMID 27017379, 2016). "The overexpression of galectin-4 has also been shown in hepatocellular carcinoma and gastric cancer cells with increased metastatic potential at the mRNA level." (PMID 24339976, 2013). "Finally, we identified a gene set associated with the differentiation status of gastric cancer, including AGR3, CLDN3, CLDN4, FABP1, LGALS4, PHGR1, MYH14 and S100A14." (PMID 36729271, 2023). "Based on these data galectin-3 and probably galectin-4 might be useful tumor markers for gastric cancers with respect to tumor progression and potentiality of lymph node metastasis especially in certain histological types of gastric cancer." (PMID 23658855, 2010). "Therefore, we hypothesized that inhibiting the binding activity of galectin-4 could also suppress the metastasis of gastric cancer." (PMID 41009793, 2025).